DICER1 (dicer 1, ribonuclease III)
Diseases named in the same sentence as DICER1 in open-access papers (continued):
Sharing a sentence is not in itself a finding about the gene and the disease.
tumor (continued). "However, as these missense variants in the Platform domain render DICER1 unable to bind pre-miRNA stem-loops, they are highly likely to be disease-associated alleles, and if occurring in a person with a tumor harboring a canonical RNase IIIb somatic mutant in trans, would be causal for DTPS." (PMID 37333613, 2023). "DICER1 tumor predisposition could present suggestive features such as macrocephaly, retinal abnormalities, multinodular goiter, renal alterations (cystic nephroma, abnormal of the collecting system of the kidney), nasal chondromesenchymal hamartoma, and dental anomalies." (PMID 37239385, 2023). "The three clusters of LGMT DICER1, SARC DICER1 and PIS DICER1 identified by our methylation analyses combined multiple well established clinicopathological tumor entities which are known to be highly associated with the DICER1 syndrome and which may exhibit considerable morphological overlap." (PMID 36966138, 2023). "The occurrence of a bi-allelic hotspot mutation at the catalytically important residues in Dicer1 and the subsequent reduced processing of 5p derived miRNAs documented by small RNA sequencing is strongly suggestive for a functional cancer-driving role in the affected tumor." (PMID 29492199, 2018). "Furthermore surgeons should subsequently be vigilant for associated DICER1 related tumours, as due to their location NCMHs may be the ‘herald tumour’ for this disease spectrum." (PMID 26138824, 2015). "In addition, Dicer1 mutations are associated with many tumors, and Dicer1 functions as a haploinsufficient tumor suppressor, and so mammalian Ago(anti) mutations could predispose cells to tumor formation." (PMID 24763381, 2014). "Clinicians should be aware of a potential germline DICER1 variant when evaluating MNG in young patients, especially if it coexists with other neoplasms." (PMID 40076617, 2025). "Future studies should include these assays to better understand the role of DICER1 in the tumor microenvironment." (PMID 40666073, 2025). "Additional preclinical work suggests that RAS/ERK pathways also lead to phosphorylation, and thus activation, of DICER1, contributing to tumor development and invasion." (PMID 40634537, 2025). "The results indicated that DICER1 expression was significantly lower in tumor tissues compared to normal tissues (P < 0.05)." (PMID 40666073, 2025). "This review recapitulates how DICER1 works in the body and what goes wrong in the process of tumor development." (PMID 40940982, 2025). "Although expressed in several tumor types, PRAME was found to be the most upregulated gene in pituitary blastoma, a tumor that is part of the DICER1-associated tumor spectrum." (PMID 40448797, 2025). "In most DICER1-related tumours, there is a heterozygous germline loss-of-function P/LPV and a tumour-specific acquired somatic P/LPV in one of five hotspot codons on the wild type allele." (PMID 40361475, 2025). "Future research should also aim to establish the causal relationship between DICER1 and TMB through additional molecular biology experiments, and validate the tumor-suppressive role of DICER1 and its correlation with TMB in animal models and clinical samples." (PMID 40666073, 2025). "Statistically significant associations were found between DICER1 expression and tumor size (P = 0.002), AJCC tumor staging (P = 0.043), and molecular typing (P = 0.028)." (PMID 40666073, 2025). "Concurrent with the germline and somatic mutations of DICER1, a pathogenic mutation in the CTNNB1 gene was also confirmed in our present tumor, which would explain the activation of the WNT/β-catenin in the morular structures." (PMID 40892116, 2025). "In the TCGA-BRCA cohort, DICER1 expression was significantly downregulated in tumor tissues compared to normal tissues." (PMID 40666073, 2025). "Herein, we report a pediatric case of this rare tumor, including pathological findings, DICER1 gene analysis of the tumor and peripheral blood samples, and the disease course." (PMID 40861331, 2025).
tumor (continued). "Numerous studies have determined the full range of DICER1 functions and the corresponding relationship to tumorigenic and non-neoplastic diseases." (PMID 39857323, 2025). "Let-7 family members, along with miR-9 and miR-146b-5p, are all downregulated 5p miRNA strands seen in DICER1 neoplasms." (PMID 40940982, 2025). "Mice given metformin had a decrease in tumor growth, an increase in DICER1 gene expression, and an elevation of microRNAs." (PMID 39857323, 2025). "Bioinformatics analysis of DICER1 expression in the TCGA-BRCA cohort revealed significant differences in DICER1 expression between normal and tumor tissues, as well as across different tumor stages (Stage I-IV) and T stages (T1-T4)." (PMID 40666073, 2025). "The DICER1 gene is thought to be a tumor suppressor gene, as its gene products interact to modulate posttranscriptional gene silencing." (PMID 39963649, 2025). "Some DICER1 syndromic neoplasms also follow a pattern of presentation closely aligned with the patient’s age." (PMID 38254836, 2024). "At germline level, these genes are known to cause at least three distinct genetic syndromes, with clinical manifestations that range from tumor predisposition (DGCR8 and DICER1 germline mutations) to neurodevelopmental disorders (AGO1/2 germline mutations)." (PMID 38607000, 2024). "In the thyroid gland, the presence of two specific neoplasms, thyroblastoma and PDTC of childhood and adolescence suggests a non-syndromic somatic DICER1 mutation as a genetic driver of the disease." (PMID 38254836, 2024). "Low DICER1 expression was significantly correlated with advanced tumor stages (p = 0.007), whereas low DROSHA expression was associated with suboptimal surgical cytoreduction outcomes (p = 0.02)." (PMID 39596271, 2024). "DICER1-syndrome usually harbors biallelic pathogenic variants: a germline LOF pathogenic variant in one allele that can occur in any domain, and a tumor-specific pathogenic somatic variant in exons encoding the RNase IIIb domain of the second allele." (PMID 38607000, 2024). "In total, 13 patients (13%) carried a P/LP variant in a known autosomal dominant tumor predisposition gene: APC (n = 1), BRCA2 (n = 2), CHEK2 (n = 4), DICER1 (n = 4), HOXB13 (n = 1), and MITF (n = 1)." (PMID 38415346, 2024). "Despite this, we chose to include them in the whole-exome sequencing analysis because potential biallelic inactivation of DICER1 would support its role as a driving force behind tumor development in these patients." (PMID 38252873, 2024). "In total, 13 of 97 patients (13%) carried a germline (likely) pathogenic variant in a well-known tumor predisposition gene: APC (n = 1), BRCA2 (n = 2), CHEK2 (n = 4), DICER1 (n = 4), HOXB13 (n = 1), and MITF (n = 1)." (PMID 38415346, 2024). "This tumor represented the primary condition in the spectrum of DICER1-related tumors, such as ovarian sex cord-stromal tumors and thyroid gland nodular hyperplasia." (PMID 39583508, 2024). "DNA methylation revealed the tumour clustered in the group known as primary intracranial sarcoma, DICER1 mutant (score > 0.9)." (PMID 37248399, 2023). "The DICER1 protein deficit is interfering with miRNA output, therefore interfering with post-transcriptional gene regulation, leading to neoplasm development." (PMID 37509342, 2023). "DICER1 damage induces a variety of tumorigenesis and tumor metastasis and functions as a tumor suppressor." (PMID 37495108, 2023). "Transcriptomics indicates that DICER1 tumors are RAS-like, whereas the ROS1-mutated tumor displays a borderline RAS-/BRAF-like subtype." (PMID 37867524, 2023). "Aside from its role as a tumor driver, reduced DICER1 expression due to haploinsufficiency or other mechanisms correlates with bad outcomes in multiple types of cancer." (PMID 38067388, 2023).
tumor (continued). "Our patient cohort comprised tumor tissue of ten C19MC-amplified cases and one DICER1 mutated ETMR case which we in part previously published." (PMID 37020088, 2023). "Methylome analysis revealed an epi-signature typical of a primary intracranial sarcoma, DICER1-mutant, an extremely rare tumor." (PMID 36831778, 2023). "Immunohistochemically, the tumor stained positively for DICER1, Desmin, and several neurogenic markers." (PMID 36153506, 2022). "Although PPB is a rare tumor, accounting for 0.25–0.5% of malignant lung neoplasms, and typically presents in infants and children younger than 6 years old, germline PVs of DICER1 have been reported to be found in about 70% of PPB cases." (PMID 35163487, 2022). "The designation of DICER1 and DROSHA as CPGs is not surprising given their fundamental roles in microRNA (miRNA) biogenesis as miRNA genes are well-known oncogenes and tumor suppressors and there is a diverse spectrum of cancers observed in DICER1 syndrome." (PMID 33987182, 2021). "Taken together, our results suggest that increasing Dicer1 expression markedly increased the expression of a broad range of tumor progression markers." (PMID 33763118, 2021). "In summary, we demonstrate that the miRNA biogenesis enzyme DICER1, acting as a tumor suppressor, is finely regulated in thyroid cells." (PMID 33176626, 2021). "However, more detailed comparative studies investigating the clinical and molecular characteristics of such rare DICER1-associated neoplasms arising in different anatomical locations are needed in order to clarify whether such tumors are in fact part of the same biological tumor spectrum." (PMID 33846547, 2021). "Strikingly, over 80% of the tumor areas from platelet Dicer1-deleted mice were grade 4, compared with just over 11% grade 4 areas in tumors from control mice at the 21 day endpoint." (PMID 34936674, 2021). "The results based on GEPIA demonstrated that the mRNA expression level of DICER1 was significantly lower in carcinoma group compared to non-tumor group (P < 0.05)." (PMID 35197926, 2021). "Among DICER1-wt ERMS 7/9 patients of our series suffered tumor recurrences or died of disease (median follow-up time: 5.5 years, range: 1–15 years)." (PMID 33846547, 2021). "In paired comparisons of the same patients, DICER1 and LRP1B were distinctly mutated only in tumor samples obtained after brachytherapy using rare-variant association tests (P = 0.01, 0.01, respectively)." (PMID 34545149, 2021). "Previously, it was shown that the Dicer1 single copy deletion in human cancers provides a relevant mechanism for impaired miRNA biogenesis, suggesting a broad role for Dicer1 as a tumor suppressor." (PMID 34722255, 2021). "Only one third of DICER1 carriers present a neoplasm during the life, hinting that multiple additional events are required." (PMID 33552988, 2020). "The DICER1-GABPA partnership constitutes a novel tumour suppressor axis in FTC with possible implications for future therapeutic interventions using miRNA-based strategies." (PMID 32163919, 2020). "GABPA has tumor suppressor roles as well through the regulation of DICER1, which is responsible for multiple tumor suppressor mechanisms involving the miRNA pathway." (PMID 33257697, 2020). "Since familial MNG and SLCT are known to predominantly be caused by DICER1 mutations, we next performed a targeted NGS analysis of plasma samples and postoperative tumor tissues from both the patients." (PMID 32629665, 2020). "To clarify these genetic observations with respect to human tumor data, we sought the existence of secondary disabling events in DICER1 hotspot cases." (PMID 31417090, 2019). "In our in vivo studies, anti-miR-146b treatment suppressed tumor growth and reversed DICER1 expression." (PMID 30967628, 2019). "Overall, our data confirm DICER1 as a tumor suppressor and show that oncogenic miR-146b contributes to its downregulation." (PMID 30967628, 2019).
tumor (continued). "This suggests that restoration of DICER1 expression by intratumoral inhibition of miR-146b contributes, at least in part, to tumor growth reduction." (PMID 30967628, 2019). "Overall, these data unequivocally establish a role of DICER1 as a tumor suppressor in thyroid follicular cells, confirming previous data demonstrating this tumor suppressor effect in other tumor types." (PMID 30967628, 2019). "Previously, higher expression of DICER1 was repeatedly detected in tumor tissue of CRC patients with poor survival." (PMID 31510013, 2019). "This is supported by our data in DICER1-silenced cells where the expression of tumor suppressors miR-30a and miR-100 recover the normal thyroid phenotype." (PMID 30967628, 2019). "Consistent with its activity against other types of tumors, the enhancement of DICER1 complex enzymatic activity by enoxacin resulted in an increase in the expression of all tested mature miRNAs, including tumor suppressor miRNAs." (PMID 30967628, 2019). "We return to the apparent tumor bias of DICER1 RNase IIIa/b inactivation in subsequent gene expression analyses." (PMID 31417090, 2019). "We next asked if the continuous repression of DICER1 by endogenous miR-146b in aggressive thyroid cells is required for tumor growth in vivo." (PMID 30967628, 2019). "Given its tumor suppressor effect, we next sought to address further downstream DICER1 effector miRNAs relevant to this phenotype." (PMID 30967628, 2019). "Of note, thyroid metastases (n = 8) exhibited even lower levels of DICER1 than primary tumor samples or normal tissue, pointing to a role for DICER1 downregulation in tumor progression." (PMID 30967628, 2019). "Administration of the small-molecule enoxacin to promote DICER1 complex activity reduced tumor aggressiveness both in vitro and in vivo." (PMID 30967628, 2019). "Dicer1 was mainly located in the cytoplasm of the cells of non-tumor liver tissues, while weak expression of Dicer1 in the tissues of HCC was identified." (PMID 29599909, 2018). "DICER1 plays different roles depending on cell context, but is thought to be a functional tumour suppressor gene." (PMID 30306785, 2018). "Dicer1 knockdown in the MSCs of healthy controls promoted cellular senescence and tumor-supporting capacity, while decreasing the differentiation capacity." (PMID 29724992, 2018). "Typical examples included known or putative tumor suppressors, such as NF1, DICER1, PML, PDS5A, MAP3K7, and PPP2R5A, in which SF3B1 mutation resulted in usage of alternative 3′ splice sites." (PMID 30194306, 2018). "We discuss the underlying pathology, risks, and screening opportunities available to those with a mutation in this gene as SLCT is only one of a multitude of other tumours encompassing DICER1 syndrome." (PMID 30356399, 2018). "Mice treated with metformin showed reduced tumor growth and an upregulation of miRNAs and an increase in DICER1 gene expression." (PMID 29762508, 2018). "The presence of an additional somatic mutation in the remaining DICER1 allele was investigated in genomic DNA obtained from CN and ERMS available tumor samples." (PMID 28222777, 2017). "In this study we explore the significance of MYCN, HMGA2, CDKN2A and DICER1 in NSCLC tumours by gene expression analysis." (PMID 26858029, 2016). "Introduction of a Dicer1-expressing construct into the DKO mouse tumor cells significantly reduced DNA synthesis and the cell growth rate, with concurrent diminished adhesion and ZO1 epithelial staining." (PMID 27602775, 2016). "Gene expression of MYCN, HMGA2, CDKN2A and DICER1 were investigated with RT-qPCR in surgically resected NSCLC tumour tissue from 175 patients." (PMID 26858029, 2016). "However, the role of DICER1 in cancer is complicated as mouse cancer models suggest that loss of one copy of the Dicer1 gene increases tumorigenesis, whereas loss of both copies inhibits it, leading to the idea that DICER1 functions as a haploinsufficient tumor suppressor." (PMID 26990999, 2016).
tumor (continued). "Studies using cancer cells in culture and murine tumor xenografts have found that metformin inhibits tumorigenesis by upregulating DICER1, a key enzyme that processes microRNAs (miRNAs)." (PMID 26990999, 2016). "Early studies involving mouse models suggested that DICER1 functions as a haploinsufficient tumour suppressor." (PMID 25883138, 2015). "These variations of Dicer1 and Drosha expression levels among different tumor types suggest that miRNA-processing complexes act as tumor suppressors or oncogenes depending on cellular context." (PMID 26834703, 2015). "NCMH’s association with the DIECR1 mutation has very recently been established and therefore in light of this any patient with a DICER1-related tumour spectrum and new nasal or orbital symptoms should raise the suspicion of NCMH." (PMID 26138824, 2015). "These latter observations seem to indicate that, in mice, Dicer1 is a haplotype insufficient tumor suppressor." (PMID 23641362, 2013). "Further studies are warranted to establish the function of miR-192 and Dicer1 in NB tumor progression." (PMID 24223844, 2013). "It is known that 22% of primary NB tumors harbor tumor deletion of chromosome 14q23-32, which includes the Dicer1 locus." (PMID 24223844, 2013). "We also observed significant changes in AGO2, DICER1 and DROSHA expression in relation to ER status, with AGO2 and DROSHA being higher and DICER1 lower in ER- tumor samples." (PMID 17922911, 2007). "Moreover, pri‐miR‐93‐1/‐2 and the miRNA‐processing enzymes DROSHA and DICER1 were undetectable in RBCs, whereas mature miR‐93‐5p increased after exposure to tumor‐derived exosomes (p < 0.05)." (PMID 41159542, 2026). "Definitive resection pathology established PPB, type III, and tumor next-generation sequencing detected a pathogenic DICER1 variant (germline status not yet confirmed)." (PMID 42290764, 2026). "Since reduced tumor size in RET/PTC3 Dicer1(−/−) thyroids may result from increased cell death, we first examined apoptosis, which converges on caspase 3/7 activation." (PMID 41002430, 2025). "Tumor IVA also revealed somatic DICER1 p.(Asp1709Gly) pathogenic variant in both tumor components, with no further molecular alterations." (PMID 40448797, 2025). "It has been suggested that DICER1 is a haplo-insufficient gene that suppresses tumor growth." (PMID 39857323, 2025). "This substantiates the notion that DICER1 is a tumor suppressor gene that aligns with the two-hit hypothesis of tumorigenesis." (PMID 40361440, 2025). "However, stochastic events cannot explain tumor formation in its entirety, since DICER1-related tumors arise only in a limited set of tissues." (PMID 40940982, 2025). "The majority of neoplasms arising in the context of the DICER1 syndrome, follows an alternative form of Knudson’s “two-hit” hypothesis." (PMID 40940982, 2025). "Additionally, the effects of DICER1 expression levels on drug sensitivity and the tumor immune microenvironment were analyzed." (PMID 40666073, 2025). "Overall, further research is necessary to unravel the cell-of-origin of the respective tumor types and whether other, hitherto undescribed, genetic factors may contribute to the development of ETMR and DICER1-associated intracranial sarcomas." (PMID 40361440, 2025). "This second variant does not lead to the full inactivation of DICER1 and therefore it does not classify as a tumor suppressor gene." (PMID 40940982, 2025). "The presence of a mix of two different tumor types, as well as immunohistochemical features, may point a pathologist towards suggesting genetic evaluation for a tumor syndrome such as DICER1." (PMID 39963649, 2025).